TCF4 (transcription factor 4)
Diseases named in the same sentence as TCF4 in open-access papers (continued):
Sharing a sentence is not in itself a finding about the gene and the disease.
colorectal cancer (continued). "Immunohistochemical analyses of LEF-1, TCF4 and nuclear β-Catenin were done using a tissue microarray with 214 colorectal cancer specimens." (PMID 21092222, 2010). "TNFRS21 is an example of a gene that did not change its expression level in the presence of exogenous Wnt expression; however, this gene has been reported as Wnt target by ChIP with colorectal cancer cell lines and TCF4 antibodies." (PMID 20515496, 2010). "LEF-1 expression was found in 56 (26%) and TCF4 expression in 99 (46%) of colorectal carcinomas and both were heterogenously distributed throughout the tumours." (PMID 21092222, 2010). "In this study we investigated the expression of β-Catenin, LEF1 and TCF4 in colorectal carcinomas and their prognostic significance." (PMID 21092222, 2010). "Although it is generally assumed that binding of β-catenin to members of the TCF/LEF family is cancer-promoting, recent studies have indicated that TCF-4 functions instead as a transcriptional repressor that restricts breast and colorectal cancer cell growth." (PMID 19924301, 2009). "Collectively, our findings suggest that Tcf4 not only regulates secretory cell lineage specification but also modulates tumor cell identity, potentially influencing tumor-microbiome interactions in colorectal cancer." (PMID 40221753, 2025). "In lung cancer, TRIB3 has been reported to facilitate tumor progression by interacting with EGFR; Similarly, TRIB3 has been shown to enhance the stemness of cancer cells and drive the progression of colorectal cancer and glioma by interacting with β-catenin and TCF4." (PMID 39881875, 2024). "TCF4 is the most downstream transcription factor in Wnt/β‐catenin signaling and forms a transcription complex with β‐catenin to promote expression of their target genes, which is considered significant for colorectal cancer growth." (PMID 38425293, 2024). "PARP-1 is TCF-4/β-A novel co activator of gene transactivation induced by catenin may play a role in the development of colorectal cancer." (PMID 38907095, 2024). "Then, we explored the involvement of ER stress roles of TCF4 in colorectal cancer." (PMID 37337284, 2023). "In addition, the expression level of TCF4 in colorectal cancer cells was inhibited by oridonin, which further affected the transcriptional regulation of downstream ER stress-related target genes by TCF4." (PMID 37337284, 2023). "In addition, claudin 7 expression is influenced by the activity of the WNT/TCF4 pathway in colonic epithelium and colorectal cancers in a manner that depends on the presence of transcription factor SOX9." (PMID 37998722, 2023). "Additionally, TRIB3 interacts with β-catenin and TCF4 to increase the stem cell features of colorectal cancer stem cells and trigger tumorigenesis." (PMID 35726370, 2022). "Taking together, these findings implied that TCF4 might play a vital role in TAMs recruitment and M2 polarization in the process of colorectal cancer liver metastasis." (PMID 34580284, 2021). "β‐catenin/TCF‐4‐induced, secreted Exos showed miRNA‐146a‐5p (miR‐146a) as the predominant miRNA to target Numb, a protein crucial for asymmetric cell division during development, in recipient colorectal cancer cells promoting stemness and tumorigenicity." (PMID 33207034, 2021). "Importantly, Pearson’s correlation analysis indicated that TCF4 expression was correlated with TAMs numbers in the colorectal cancer samples and M2 macrophage markers expression." (PMID 34580284, 2021).
colorectal cancer (continued). "Therefore, the present study investigated the mutational analysis of exon 1 of the TCF-4 gene and the expression analysis of TCF-4 in sporadic colorectal cancer patients in a north Indian population." (PMID 32265994, 2020). "REG4 promotes colorectal cancer cell division through Akt/GSK-3β/β-catenin/TCF-4 pathway." (PMID 33489872, 2020). "Moreover, DDX3X silencing by siRNA causes reductions in both TCF-4 reporter activity and TCF-4-mediated modulation of downstream target genes in colorectal cancer, which leads to reduced proliferation and G1 arrest." (PMID 31906196, 2019). "Furthermore, it was reported that β-catenin/TCF4 complexes bind a DNA enhancer element within the first intron of the YAP gene to drive YAP expression in colorectal carcinoma cells, thus highlighting a physical interaction at the DNA level." (PMID 31228951, 2019). "Also in colorectal cancer cells, transient expression of TCF4 significantly rescued SFN-induced inhibition of Wnt/β-catenin signaling." (PMID 30338040, 2018). "Similarly, a diterpenoid henryin has been recently shown to interfere with β-catenin/TCF4 interaction in colorectal cancer cells." (PMID 28887754, 2018). "Moreover, recent genetic analysis of human tumor specimens indicated a possible tumor suppressive role of TCF4 in a significant fraction of colorectal carcinomas." (PMID 30200414, 2018). "In addition, Daxx potentiates TCF4/β-catenin-mediated transcriptional activation in colorectal cancer cells." (PMID 26205068, 2016). "It has been demonstrated that Wnt/β-catenin signaling plays an important role in the maintenance of radioresistant aldehyde dehydrogenase positive (ALDH+) prostate cancer cells, and that silencing of the Wnt transcription factor TCF4 sensitizes colorectal cancer cells to (chemo-) radiotherapy." (PMID 27363012, 2016). "The aim of the current study is to investigate if TCF4 could be a molecular target of phytochemicals in human colorectal cancer cells." (PMID 25961950, 2015). "Taken together, our data indicate that TCF4 may sensitize the proapoptotic activity of resveratrol in human colorectal cancer cells." (PMID 25961950, 2015). "A lot of studies have demonstrated that the β-catenin/TCF-dependent signaling pathway is a molecular target for the chemoprevention of phytochemicals, and we reported that capsaicin suppressed the expression and protein interaction of β-catenin and TCF4 in human colorectal cancer cells." (PMID 25961950, 2015). "All phytochemicals tested down-regulated TCF4 expression, proposing that down-regulation of TCF4 could be a potential anti-cancer mechanism by phytochemicals in human colorectal cancer." (PMID 25961950, 2015). "Moreover, HIF-1α competes with transcription factor 4 (TCF4) for direct binding to β-catenin thereby enhancing EMT in colorectal cancer." (PMID 26057751, 2015). "Wnt3a and Wnt mimetics significantly enhanced the expression of PLDs at a transcriptional level in HCT116 colorectal cancer cells, whereas silencing of β-catenin gene expression or utilization of a dominant negative form of T cell factor-4 (TCF-4) inhibited expression of PLDs." (PMID 20711340, 2010). "Furthermore, CD44 expression is, directly or indirectly, regulated by the β-catenin/Tcf-4 signaling pathway, especially in the colorectal cancer precursor lesions, suggesting a role for CD44 in intestinal tumorigenesis." (PMID 20696077, 2010). "These surprising findings suggest that TCF4 might be the main binding partner for β-catenin during development and progression of colorectal cancer whereas an enhancement of Wnt/β-catenin transcriptional activity by a switch from TCF4 to LEF-1 is unlikely." (PMID 21092222, 2010). "In contrast LEF-1 expression was found only in 26% and TCF4 in 46% of colorectal carcinomas." (PMID 21092222, 2010). "Furthermore, we show 1,25(OH)2D3 increases TCF-4 at the RNA and protein levels in several human colorectal cancer cell lines, the effect of which is completely dependent on the VDR." (PMID 19924301, 2009).
colorectal cancer (continued). "Consequently, to further determine the effects of VDR and its classical ligand on TCF-4 expression, we assayed several colorectal cancer cell lines for changes in TCF-4 expression in response to 1,25(OH)2D3." (PMID 19924301, 2009). "However, in the context of human CRC, the TCF4 role remains unclear, particularly because inactivating mutations in the TCF7L2 gene are relatively common in advanced stages of human colorectal cancer." (PMID 40221753, 2025). "Thus, it is worth to verify experimentally whether the IFNγ/IFNGR2/APC/TCF4/GPX4 axis exists in colorectal cancer cells that, once taking on actions, triggers ferroptosis in colorectal CSCs." (PMID 37671945, 2023). "Furthermore, according to the detection and analysis of multiple tumor cell lines, the protein and mRNA expression levels of TCF4 were higher in colorectal cancer HCT116, LoVo, SW480, and RKO cell lines than NCM460, a normal intestinal epithelial immortalized cell line." (PMID 37337284, 2023). "Importantly, seminal work published back-to-back in Science show APC mutant colorectal cancers fail to regulate β-catenin, which permit constitutive transcriptional activation of a β-catenin/TCF-4 complex, thus driving Wnt signalling in colorectal cancer tissue." (PMID 29570681, 2018). "Therefore, compared to β-catenin knockdown, Tcf-4 knockdown shows better efficacy for inhibiting proliferation and inducing apoptosis of colorectal cancer cells, which may be related to increased FOXO4 transcriptional activity." (PMID 23029137, 2012). "As LEF-1 is not expressed in the normal colon mucosa, but is found in human colorectal cancer, a shift of β-catenin binding partners from TCF4 to LEF-1 might occur during carcinogenesis which might enable enhanced epithelial-mesenchymal transition (EMT) and malignant progression." (PMID 21092222, 2010). "Furthermore, in colorectal cancer cells that have overactive β-catenin, TCF-4 is known to be growth inhibitory, as RNAi-mediated disruption of its expression facilitates β-catenin activity and cell growth in both DLD-1 cells (APC mutation) and HCT116 cells (activating β-catenin mutation)." (PMID 19924301, 2009). "In colorectal cancer, it appeared that CREPT interacts with β-catenin, TCF4, and p300 to regulate Wnt signaling pathway." (PMID 40860160, 2025). "In colorectal cancer stem cells, TRIB3 can interact with β-catenin and Tcf4 to increase AOM/DSS-induced colorectal tumor formation and xenograft tumor growth in mice." (PMID 37875976, 2023). "For example, in the context of colorectal cancer, it was demonstrated that PARP1 binds transcription factor TCF4 and interacts in a complex with TCF4 and β-catenin contributing to early colorectal carcinogenesis." (PMID 34686201, 2021). "Regarding activation of EMT-TFs, a previous study in colorectal cancer reported that ZEB1, one of the core EMT-TFs, was activated through the β-catenin/TCF4 complex." (PMID 34356119, 2021). "HIF-1α also binds to β-catenin by competing with transcription factor 4 (TCF4), thereby inducing EMT in colorectal cancer." (PMID 30671168, 2018). "In colorectal cancers it has been shown that β-catenin/TCF4 complexes compete with TCF3 to bind to the MYC promoter, and β-catenin/TCF4 induces its expression while TCF3 represses it." (PMID 27228072, 2016). "The β-catenin/TCF4 complex, a critical oncogenous complex, binds directly to the ZEB1 promoter and activates its transcription, thereby leading to EMT in colorectal cancer." (PMID 25871400, 2015). "Unlikely TCF4, the basal level of β-catenin was high in SW480 cells and relatively lower in other colorectal cancer cell lines." (PMID 25961950, 2015). "The first class represents the majority of the DNA-bound β-catenin and co-localizes with TCF4, the prominent TCF/LEF family member in murine intestinal epithelium, Wnt-responsive colorectal cancer cells and HEK293 embryonic kidney cells." (PMID 26075748, 2015).
colorectal cancer (continued). "Decreased TCF4 represses β-catenin/TCF-dependent transcriptional activity and enhances the proapoptotic activity of resveratrol in human colorectal cancer cells." (PMID 25961950, 2015). "The present study describes another mode of crosstalk between the VDR and β-catenin pathways by demonstrating that TCF7L2/TCF-4, itself, is regulated by VDR/1,25(OH)2D3 in human colorectal cancer cell lines and likely in the mammary gland as well." (PMID 19924301, 2009). "Among these, the largest reduction in stability is observed for the TCF7L2/TCF-4 tumour suppressor (more than 2 PSI units) that regulates the WNT signalling pathway and transactivates downstream target genes involved in the progression of colorectal cancer." (PMID 40276932, 2025). "Among these, many have important roles in regulating the neural progenitors migration, such as deleted in colorectal cancer (DCC), XKR6 and transcription factor 4 (TCF4)." (PMID 36729042, 2023). "Similarly, in colorectal cancer, HOXB13 downregulated the protein expression of TCF4, thereby hindering the cell growth." (PMID 33479226, 2021). "Consistent with our result, a previous study showed that β-catenin and TCF4, a member of T-cell and lymphoid enhancer (TCF/LEF) factor family, could bind to and regulate MIR17HG promoter in colorectal cancer." (PMID 31191623, 2019). "T-cell factor-4 (TCF4) is a member of the TCF/LEF (lymphoid enhancer factor) family of transcription factors, and dysregulation of β-catenin is decisive for the initiation and progression of colorectal cancer." (PMID 25961950, 2015). "We do not know why resveratrol down-regulates TCF4 in a cell-type-specific manner in human colorectal cancer cells." (PMID 25961950, 2015). "We also observed that NSAIDs (Non-steroid anti-inflammatory drugs), such as tolfenamic acid, decreased the expression of TCF4 in human colorectal cancer cells (data not shown)." (PMID 25961950, 2015). "TCF4 was not expressed in normal colon cells, but highly expressed in human colorectal cancer cell lines, including HCT116, LoVo and Caco-2 cells." (PMID 25961950, 2015). "Preliminary attempts to detect K150 acetylation after immunoprecipitation of TCF4 from colorectal cancer cells were not successful (A. W., S. E. and A.H., unpublished)." (PMID 23613959, 2013). "In colorectal cancer the expression of TCF4 as well as LEF-1 has been described, but was not accurately evaluated and compared with nuclear β-catenin positivity." (PMID 21092222, 2010). "TCF4 expression does not correlate with age, gender or T-category of the investigated colorectal cancer cases." (PMID 21092222, 2010). "The DNA binding proteins and transcription factors TCF4 and LEF-1 are partners of nuclear β-catenin and effectors of the Wnt/β-catenin signalling pathway, which is decisively involved in tumorigenesis and progression of colorectal cancer." (PMID 21092222, 2010). "Although β-catenin/TCF4-mediated ABCB1 expression represents only one mechanism within the complex transcriptional regulation of the ABCB1 gene, our findings on the dominant action of gain-of-function β-catenin adds to the current knowledge on the role of ABCB1 in the biology of colorectal cancer." (PMID 22460269, 2012). "In colorectal cancer cells, WNT/TCF4 activation in the absence of SOX9 leads to high claudin 7 expression, which has diffuse localization in the basolateral membrane and favors loss of polarity." (PMID 37998722, 2023). "The present study establishes that the nuclear expressions of TCF4, LEF-1 and β-catenin do not correlate with each other and that TCF4 and LEF-1 positivity is not mutually exclusive in colorectal cancer." (PMID 21092222, 2010).
colon carcinoma (105 papers, 2005 to 2026). "Mutations in the Wnt components, specifically TCF4, were found in microsatellite-unstable colon cancers." (PMID 39859530, 2025). "TCF4 is capable of attenuating the proliferation of colon cancer and medulloblastoma cells, whereas loss of TCF4 exerts the opposite effect, favoring tumorigenesis." (PMID 36084949, 2022). "The main binding partner of β-catenin in the colon is TCF4, but colon tumors isolated from APC mutated mice have an increased expression of LEF1 and TCF1." (PMID 29975781, 2018). "Significantly increased binding of pβ-Cat552 to TCF4 was also detected in colon cancer cell lines with different mutations in β-catenin signaling pathway - Caco2, SW480, HT29 and HCT116." (PMID 29330435, 2018). "qRT-PCR analysis of xenograft tumors from a colon cancer cell line showed MCT-1 downregulation in the presence of dnLEF/TCFs, and ChIP-seq ENCODE data shows TCF-4 occupancy of SLC16A1 in HCT116 colon cancer cells." (PMID 27729975, 2016). "The β-catenin/TCF4 complex induces the epithelial-to-mesenchymal transition (EMT)-activator ZEB1 to promote tumor invasion in APC-mutated colon cancer." (PMID 27007150, 2016). "The β-catenin/TCF4 complex is localized into the nucleus, where it leads to up-regulation of downstream targets in colon cancer and is implicated in colorectal tumorigenesis." (PMID 25961950, 2015). "Because positioning of the distal elements A-E with the MYC promoter was detected in non-colon cancer cells lines that lack chromatin associated ß-catenin/TCF4 complexes, it is unlikely that these factors are required to form the chromatin loops." (PMID 21533051, 2011). "ITF2 is implicated as both a tumor suppressor and proto-oncogene in colon cancer; relevant to the current analysis, in human colon cancer cells and tissue, ITF2 is reported to prevent activation of the β-catenin-TCF4 complex and transcription of β-catenin gene targets." (PMID 35370785, 2022). "In addition, ChIP assay showed that both elements associate with TCF4/β-catenin complex in colon cancer cells." (PMID 24466159, 2014). "Loss of a tumor suppressor causes activation of β-catenin/TCF4 in colon cancers." (PMID 20459822, 2010). "Daxx interacts with Tcf4 and inhibits its transcriptional function, thereby modifying downstream gene expression of Tcf4 and facilitating G1 arrest in colon cancer cells." (PMID 40296918, 2025). "This study highlights the critical role of Tcf4 in regulating cell fate in both healthy intestinal epithelium and colon tumors." (PMID 40221753, 2025). "In colon tumors, Paneth-like cells form a tumor cell population, express Wnt ligands, and require Tcf4 for their identity." (PMID 40221753, 2025). "Quercetin, which belongs to the flavonol family, attenuate Wnt/β-catenin signaling by decreasing nuclear β-catenin and Tcf-4 expression in SW480 colon cancer cells." (PMID 37463866, 2023). "REV7 depletion suppresses E-cadherin expression via upregulation of SLUG and promotes TCF4-mediated epithelial–mesenchymal transition (EMT) in colon cancer cells." (PMID 36980607, 2023). "Immunoprecipitation assays using nuclear extracts derived from HCT116 colon cancer cells incubated with increasing concentrations of Flag-βPix revealed progressively augmented Flag-βPix and β-catenin binding to TCF-4." (PMID 37805544, 2023). "The increased expression of PPAR-β/δ mRNA in colon cancers has been attributed to APC-β-catenin-TCF4-mediated transcription, similar to the well-known target gene β-catenin-TCF4 CCND1, which encodes cyclin D1." (PMID 35203272, 2022). "The interaction between FXR and β-catenin impairs β-catenin/TCF4 complex formation to inhibit the progression of colon cancer." (PMID 35999582, 2022).